SRGN (serglycin)
Diseases named in the same sentence as SRGN in open-access papers (continued):
Sharing a sentence is not in itself a finding about the gene and the disease.
breast carcinoma (continued). "Furthermore, invasiveness and mobility of the cells was shown to be dependent on the glycosylated form of serglycin in breast cancer." (PMID 35494005, 2022). "SRGN further plays an important role in chemoresistance and stemness of breast cancer cells." (PMID 36358747, 2022). "Similarly, to breast cancer, serglycin triggers signaling pathways that evoke malignant properties and EMT in many other cancer types." (PMID 35494005, 2022). "SRGN/TGFβ2 interlay establishes a positive feedback loop that promotes EMT in breast cancer cells." (PMID 36358747, 2022). "Serglycin is constitutively secreted by breast cancer cells acting in an autocrine manner via binding to cell surface receptors such as CD44, a key mesenchymal and breast cancer stem cell marker gene, and integrins, possibly through its chondroitin sulfate (CS) chains." (PMID 35494005, 2022). "Although immunohistochemical studies showed increased SRGN expression in aggressive breast carcinoma 10,11, nasopharyngeal carcinoma 12, and other types of cancer 13, little is known about the diagnostic or prognostic significance of circulating SRGN in patients with cancer." (PMID 33456569, 2021). "Subsequently, we investigated the clinical relevance of SRGN in breast cancer." (PMID 32292495, 2020). "Serglycin (SRGN) is a low molecular weight glycoprotein involving in breast cancer metastasis." (PMID 28692037, 2017). "In the present study we report that genetic ablation of serglycin proteoglycan completely blocks lung metastasis in the MMTV-PyMT-driven mouse breast cancer model, while serglycin-deficiency did not affect primary tumour growth or number of mammary tumours." (PMID 27223472, 2016). "Together, this indicates that serglycin affects the inflammatory response and may regulate the overall inflammation level in the mammary tumours." (PMID 27223472, 2016). "Our results show that serglycin is essential for the metastatic capacity of mammary tumour cells." (PMID 27223472, 2016). "We therefore next speculated that the deletion of serglycin possibly could affect the total expression level of GAGs in mammary tumour tissue." (PMID 27223472, 2016). "In recent years, expression of serglycin has also been found in different forms of human malignancies and a high serglycin expression level has been correlated with a more migratory and invasive phenotype in the case of breast cancer and nasopharyngeal carcinoma." (PMID 25978773, 2015). "Furthermore, the establishment of aggressive breast cancer phenotype following upregulation of NEDD9 is accompanied by increased expression of serglycin, its cell surface binding partner CD44, and CS synthesizing enzymes." (PMID 26581653, 2015). "Therefore, the specific structure of CS-4 present on serglycin is important for serglycin functions in breast cancer." (PMID 24455486, 2014). "This study suggests that serglycin promotes a more aggressive cancer cell phenotype and may protect breast cancer cells from complement attack supporting their survival and expansion." (PMID 25140302, 2014). "Furthermore, serglycin is highly expressed by other aggressive breast cancer cells, which also belong to the Basal B subgroup, and they show mesenchymal phenotype, enhanced invasive properties and enriched expression of EMT transcriptional drivers." (PMID 24455486, 2014). "Serglycin was over-expressed by breast cancer cells clustered into Basal B subgroup." (PMID 24205138, 2013). "To examine whether serglycin isolated from breast cancer cells exhibits a similar inhibitory profile, we measured the total hemolytic activity of the classical and the alternative complement pathways in the presence of serglycin in vitro." (PMID 24205138, 2013). "Moreover, we demonstrate high expression and constitutive secretion of serglycin in the aggressive MDA-MB-231 breast cancer cell line." (PMID 24205138, 2013). "MDA-MB-231 and MCF-7 breast cancer cells were permeabilized and stained for serglycin and F-actin." (PMID 24205138, 2013).
breast carcinoma (continued). "Our findings suggest that serglycin promotes a more aggressive cancer cell phenotype and may protect breast cancer cells from complement attack supporting their survival and expansion." (PMID 24205138, 2013). "Secreted serglycin may interact with CD44 on breast cancer cell membrane and trigger CD44 signaling promoting cancer cell migration and invasion." (PMID 24205138, 2013). "Our data have now showed that serglycin is highly expressed by aggressive MDA-MB-231 breast cancer cells, which belong to the Basal B subgroup, and they show mesenchymal phenotype, enhanced invasive properties and enriched expression of EMT transcriptional drivers." (PMID 24205138, 2013). "Notably, serglycin was ubiquitously synthesized by breast cancer cells, in all cases showing a strong cytoplasmic staining." (PMID 24205138, 2013). "Overexpression of serglycin promotes breast cancer cell growth, migration and invasion." (PMID 24205138, 2013). "Importantly, we confirmed the overexpression of serglycin in breast cancer cells in vivo in patient material by immunohistochemistry." (PMID 24205138, 2013). "Our data reveal a novel role of serglycin in breast cancer and the promotion of the disease." (PMID 24205138, 2013). "The specific structure of CS-4 present on serglycin may be important for serglycin functions in breast cancer." (PMID 24205138, 2013). "Although detailed molecular mechanisms by which cytoplasmic maspin activates SRGN/TGFβ2 axis remain to be clarified, our data suggest that cytoplasmic maspin plays a pivotal role in the aggressive phenotype and serves as a therapeutic target in patients with breast cancer, especially TNBC." (PMID 34059749, 2021). "In addition, SRGN also regulates the migration and metastasis of breast cancer and lung cancer." (PMID 34556636, 2021). "In addition to lung cancer, SRGN has also been reported to promote aggressive phenotypes in breast cancer cells by inducing epithelial-mesenchymal transition, and up-regulating the production of proteolytic activity and proinflammatory cytokines, including IL-8." (PMID 31898491, 2020). "SRGN exerts a regulatory role in the activation of IL-8/CXCR-2 and downstream signaling pathways in GBM and breast cancer cells." (PMID 38672477, 2024). "Several studies have previously investigated the interaction between SRGN and CD44, mostly in cancers, such as breast cancer and non-small cell lung cancer." (PMID 38287411, 2024). "Such an example is the cooperation of SRGN with TGFβ2 to induce EMT and breast cancer cell growth, invasion and metastasis." (PMID 38672477, 2024). "As serglycin is important for EMT and expressed by mesenchymal like breast cancer cell lines, we went on to examine the expression of SRGN in two breast cancer cohorts, TCGA and OSLO2." (PMID 35494005, 2022). "Concerning breast cancer, knockdown of SRGN in mesenchymal-like MDA-MB-231 and the induction of the SRGN expression in epithelial MCF-7 cancer cells confirmed the vital role of SRGN in the induction of EMT." (PMID 36358747, 2022). "The role of SRGN in EMT and cancer cell stemness has been confirmed in a plethora of cancer types, such as HCC, breast cancer, colorectal, lung, and nasopharyngeal cancer." (PMID 36358747, 2022). "Serglycin is highly expressed in the highly invasive, triple-negative MDA-MB-231 breast carcinoma cells." (PMID 32847060, 2020). "Serglycin remains cytoplasmic and is highly expressed in MDA-MB-231 and moderately expressed in MCF7 breast cancer cells." (PMID 32961706, 2020). "The expression of serglycin and CD44 core proteins enhanced in breast cancer cells and CS-E subunit attaches to CD44 to promote and regulate breast cancer progression." (PMID 29747682, 2018). "The possible role of serglycin in metastatic dissemination was therefore studied in the transgenic MMTV-PyMT mouse model that develops orthotopic and spontaneous mammary tumours." (PMID 27223472, 2016).
breast carcinoma (continued). "Using a binding assay with immobilized serglycin, we found that C1q and MBL bound serglycin from breast cancer cells dose-dependently." (PMID 24205138, 2013). "Serglycin secreted by aggressive breast cancer cells inhibits both the classical and the lectin pathways of complement by directly binding to C1q and MBL in a similar manner as serglycin secreted by myeloma cells." (PMID 24205138, 2013). "The role of serglycin in cancer mechanotransduction is still under investigation, and initial investigations have demonstrated its involvement in FAK signaling and YAP expression in breast cancer cells." (PMID 39334952, 2024). "Serglycin was found to upregulate YAP through integrin α5/FAK/CREB signaling, resulting in increased histone deacetylase 2 (HDAC2) expression, which modulates stemness and chemoresistance in breast cancer cells." (PMID 39334952, 2024). "We have demonstrated that the high expression of SRGN in the generally aggressive basal-like breast cancer subtype is not a consequence of gene amplification, but rather surprisingly, the subtype shows a higher probability for allele loss." (PMID 35494005, 2022). "Knockout of SRGN has no impact on the growth of primary tumor or the number of mammary tumors formed in the MMTV-PyMT-driven mouse breast cancer model." (PMID 36358747, 2022). "SRGN was also mildly expressed in bone-metastatic breast cancer cell lines SCP2 and 1833, but not in normal bone stroma cells including mesenchymal stem cells, osteoblasts and osteoclasts." (PMID 34556636, 2021). "Secreted serglycin from cancer cells was shown to be primarily CS-modified, and transgenic expression of serglycin lacking the GAG attachment site led to decreased migratory capacity of breast cancer cells in vitro." (PMID 32984308, 2020). "Although the expression of PGs in breast cancer has been extensively studied, there are no published data on the expression of serglycin." (PMID 24205138, 2013). "In agreement with data presented in our previous study, serglycin was expressed in minute levels in low aggressive MDA-MB-468 and MCF-7 cells, whereas it was expressed in elevated levels in high aggressive MDA-MD-231 breast cancer cells, which are KRAS38G→A and BRAF1391G→T mutant." (PMID 26581653, 2015). "In this study, we clearly demonstrated that serglycin secreted by MDA-MB-231 breast cancer cells exhibited a similar capacity to inhibit the classical and the lectin pathways via binding to C1q and MBL with slightly different affinities than myeloma-derived serglycin." (PMID 24205138, 2013). "CS chains of serglycin secreted by breast cancer cells did not contain detectable amounts of oversulfated disaccharides [disulfated disaccharides] found in serglycin from hematopoietic cells, such as basophils, monocytes, macrophages, connective tissue, and mucosal mast cells." (PMID 24205138, 2013). "Altogether, our data and previously published data on serglycin, EMT, and cancer, may imply that serglycin participates in an immune cell-cancer cell crosstalk, acting as a regulatory molecule that links inflammation and induced oncogenic signaling and EMT in breast cancer cell." (PMID 35494005, 2022). "Interestingly, stable overexpression of intact serglycin gene and a truncated form of serglycin lacking GAG attachment sites in low aggressive MCF-7 breast cancer cells demonstrated that serglycin promotes breast cancer cell anchorage-independent growth, migration, and invasion." (PMID 24455486, 2014).
nasopharyngeal carcinoma (22 papers, 2012 to 2025). A carcinoma arising from the nasopharyngeal epithelium. "Only few studies have shown that serglycin augmented expression is associated with cancer cell aggressiveness and disease progression in hepatocellular, breast, and nasopharyngeal cancer." (PMID 26581653, 2015). "The overexpression of serglycin is also associated with EMT in nasopharyngeal cancer cells." (PMID 24455486, 2014). "SRGN has recently been shown to be secreted by malignant cells, including multiple myeloma cells, nasopharyngeal carcinoma and NSCLC, and functioned in cell adhesion and cell migration." (PMID 31898491, 2020). "Recently, it was demonstrated that serglycin is highly expressed by aggressive nasopharyngeal cancer cells." (PMID 24455486, 2014). "Metastatic nasopharyngeal carcinoma cells highly express and secrete in the culture medium serglycin, which promotes motility, invasion, and metastasis." (PMID 24455486, 2014). "This is in agreement with findings in nasopharyngeal cancer and correlates serglycin overexpression with aggressive cancer phenotype." (PMID 24205138, 2013). "Serglycin was highly expressed by aggressive nasopharyngeal cancer cells showing a mesenchymal phenotype with high expression levels of mesenchymal markers and low levels of epithelial marker E-cadherin." (PMID 24205138, 2013). "In a recent study, high-throughput gene expression profiling analysis of nasopharyngeal carcinoma cell lines revealed the upregulation of serglycin in cells with high-metastatic potential in comparison to cells showing low-metastatic potential." (PMID 24205138, 2013). "Based on these findings, the FoxO1-miR-148a-5p-CREB1 axis is involved in STAT3-mediated regulation of SRGN and the promotion of nasopharyngeal cancer growth and metastasis, thereby confirming the role of STAT3 in the proliferation, invasion, and anti-apoptotic effects of NPC cells." (PMID 36313702, 2022). "Serglycin (SRGN) was initially identified as a secretary granule proteoglycan functioning in promoting secretory granule storage processes first in mast cells, then in many other hematopoietic cells, endothelial cells and nasopharyngeal carcinomas." (PMID 31898491, 2020). "However, SRGN has also been shown to be constitutively secreted by macrophages, multiple myeloma cells and nasopharyngeal carcinoma." (PMID 31898491, 2020). "Furthermore, high levels of serglycin were demonstrated in nasopharyngeal carcinoma cells, with higher levels in clones with increased metastatic potential and also, with higher motility." (PMID 26694746, 2015). "Increased expression of serglycin in patients with hepatocellular and nasopharyngeal carcinoma was correlated with unfavorable prognosis and represented an independent unfavorable prognostic indicator for overall survival and recurrence as well as disease free and distant metastasis free survival." (PMID 24455486, 2014). "Syndecan-1 driven upregulation of serglycin (the only constitutively intracellular proteoglycan) in mesothelioma cells can be an important new finding for cancer cell biology, as there are only a few reports linking serglycin to tumors, mostly to multiple myeloma and nasopharyngeal carcinoma cells." (PMID 23144729, 2012). "As an extracellular matrix (ECM) component, serglycin promotes nasopharyngeal carcinoma (NPC) metastasis and serves as an independent, unfavorable NPC prognostic indicator." (PMID 27809309, 2016). "The serglycin/CD44 signaling axis induces the expression of Nanog and activates NF-κB/claudin-1 axis in NSCLC and triggers MAPK/β-catenin signaling in nasopharyngeal cancer cells to foster EMT, cancer cell stemness, and drug resistance." (PMID 35494005, 2022). "Serglycin, a gene product of PRG1, is a proteoglycan that has been functionally identified as a significant regulator of metastasis in nasopharyngeal carcinoma (NPC)." (PMID 23671674, 2013).
nasopharyngeal carcinoma (continued). "Serglycin (SRGN) is a pro-tumorigenic PG expressed and secreted by a variety of aggressive tumor cells, including GBM, breast, multiple myeloma and nasopharyngeal cancer cells." (PMID 38672477, 2024). "In glioblastoma, STAT3 phosphorylation was suppressed through SRGN knockdown; in contrast, STAT3 induced SRGN in nasopharyngeal carcinoma, suggesting a potential positive feedback loop in tumor cells that may also operate in TAMs, thereby sustaining a potent oncogenic signaling circuit." (PMID 41476965, 2025).
multiple myeloma (19 papers, 2012 to 2025). "Serglycin has also been implicated in the development of the tumor vasculature in multiple myeloma and hepatocellular carcinoma where reduced expression of serglycin was correlated with a less extensive vasculature." (PMID 25978773, 2015). "Matrix secreted and cell-surface associated serglycin protects myeloma cells from complement system attack induced by immunotherapy, therefore promoting the survival of myeloma cells." (PMID 24455486, 2014). "Initial studies reported increased levels of serglycin only in hematological malignancies like multiple myeloma and leukemia; however, more recent findings suggest that serglycin is overexpressed in glioma and tumors of the breast, prostate, lung, and liver." (PMID 36693448, 2023). "Myeloma-derived EVs with serglycin engulfed by macrophages augment migration as compared with serglycin-null EVs." (PMID 36405712, 2022). "In all, in myeloma-derived exosomes, serglycin and its binding partner are transferred to target cells, by which the recipient cells are reprogrammed to facilitate cancer progression." (PMID 34722637, 2021). "Exosomal serglycin significantly promotes the proliferation and invasion of myeloma cells, and increases the migration of macrophage." (PMID 34722637, 2021). "High serglycin levels are present in bone marrow aspirates of >30% of newly diagnosed multiple myeloma patients, and are required for adhesion, in vivo growth, and vascularization of multiple myeloma cell." (PMID 30237983, 2018). "In multiple myeloma cells, the secretory-vesicle proteoglycan serglycin is the major proteoglycan expressed and constitutively secreted." (PMID 30237983, 2018). "In the study reported here, we discovered that serglycin is present in exosomes derived from the cell culture supernatants of human myeloma cell lines and from the serum of myeloma patients." (PMID 29088739, 2017). "We established for the first time that serglycin is present in exosomes derived from myeloma cell lines and the serum of myeloma patients." (PMID 29088739, 2017). "We and others have recently demonstrated that serglycin expressed by myeloma cells is decorated only by CS chains and that these CS chains are almost completely composed of 4-O-sulfated disaccharides." (PMID 29088739, 2017). "More importantly, consistent with the findings from serglycin-knockout animals, we discovered that exosomes from myeloma cells with serglycin knockdown had significantly fewer proteins than exosomes from serglycin-expressing control cells." (PMID 29088739, 2017). "Serglycin was found to be present in exosomes from all human myeloma cell lines tested, except in serglycin knocked down (SRGN-KD) CAG cells." (PMID 29088739, 2017). "Here we demonstrate a critical role of the chondroitin sulfate proteoglycan serglycin in regulating the protein cargo and functions of myeloma cell-derived exosomes." (PMID 29088739, 2017). "Because we previously showed a critical role of serglycin in myeloma cell adhesion to bone marrow stromal cells and collagen I, we next focused on proteins involved in cell adhesion pathways." (PMID 29088739, 2017). "We also showed that knockdown of serglycin in myeloma cells decreased the number of exosomal proteins and reduced the impact of these exosomes on tumor and host cells." (PMID 29088739, 2017). "We recently demonstrated that serglycin, which is commonly regarded as an intracellular PG, is constitutively secreted by myeloma cells, and can function extracellularly." (PMID 29088739, 2017). "Since serglycin has long been considered to be present within intracellular granules/vesicles, we sought to determine if serglycin is present in the intracellularly generated extracellular vesicles, exosomes, of myeloma patients." (PMID 29088739, 2017). "We previously reported that the CS GAGs attached to the core protein of serglycin constitute the major component of the myeloma glycocalyx." (PMID 29088739, 2017).